SCARNA3 (small Cajal body-specific RNA 3)
Synonyms: HBI-100
Gene: Small Cajal body-specific RNA gene on chromosome 1 (175,968,398 to 175,968,540, reverse strand). Ensembl gene ENSG00000252906.
Gene Ontology:
Biological process: RNA processing
Cellular component: Cajal body; nucleolus
Homologues: Orthologues: chimpanzee SCARNA3 (98% identical), macaque SCARNA3 (96% identical), guinea pig SCARNA3 (92% identical), rabbit SCARNA3 (88% identical).